INS (insulin)
Diseases named in the same sentence as INS in open-access papers (continued):
Sharing a sentence is not in itself a finding about the gene and the disease.
type 2 diabetes (continued). "The goal of this study was to evaluate glycemic control using the ultralong-acting basal insulin degludec (IDeg) in combination with insulin aspart (IAsp) within an algorithm-driven electronic clinical decision support system (cDSS) in inpatients with type 2 diabetes (T2D)." (PMID 42187485, 2026). "Aging and type 2 diabetes mellitus (T2DM) further exacerbate these effects by reducing insulin availability in the brain and impairing insulin receptor signaling at the neuronal level." (PMID 41596611, 2026). "Once-weekly injectable insulin products are similarly set to transform type 2 diabetes management, with evidence of greater improvement in long-term glucose control and time within normal range across seven randomised clinical trials (n = 3286, 60% on once-weekly injectable insulin)." (PMID 40956864, 2026). "Type 2 diabetes (T2D) comprises defective insulin secretion, its ineffective utilization, or both, resulting in hyperglycemia." (PMID 41599783, 2026). "Type 2 diabetes mellitus (T2DM) is a chronic condition characterized by the body’s inability to effectively use insulin, leading to high blood sugar levels." (PMID 39916706, 2025). "Additionally, the concomitant use of semaglutide with other type 2 diabetes medications, such as insulin or sulfonylureas, which promote weight gain may also reduce the weight loss effect." (PMID 40937273, 2025). "The reviewed literature showed similar and sometimes improved glycemic control when insulin icodec was compared to other long-acting insulins both in insulin-naive and previously insulin-treated patients with the data being most robust in patients with type 2 diabetes." (PMID 40156735, 2025). "In addition to its role in triglyceride metabolism, APOC3 has been implicated in type 2 diabetes mellitus (T2DM) pathophysiology through mechanisms such as promoting pancreatic β-cell apoptosis, dysregulation of glucose metabolism, and influencing insulin resistance." (PMID 40282372, 2025). "The first observation of note is that isCGM users with type 2 diabetes on insulin therapy achieve comparable and sustained reductions in HbA1c after initiating isCGM, irrespective of treatment with either intensive multiple daily injections or basal insulin-only regimens." (PMID 39460755, 2025). "Importantly, dietary weight loss in people with non-type 2 diabetes brought about no ill effects, as indeed seen with improved survival in type 1 diabetes on the very-low-energy Allen diet in the pre-insulin era." (PMID 40316731, 2025). "When lifestyle intervention and oral antidiabetic drugs (OADs) fail to provide optimal control, patients with type 2 diabetes are required to initiate injectable therapies, mostly basal insulin (BI), according to 2020 Chinese guidelines for T2DM management." (PMID 39694849, 2025). "Type 2 diabetes mellitus (T2DM) is a chronic disease that develops when the body cannot effectively produce and use insulin." (PMID 40472049, 2025). "Type 2 diabetes mellitus (T2DM) is a metabolic disease characterized by chronic hyperglycemia due to insulin secretion or utilization disorders or both." (PMID 39796606, 2025). "Because of the overconsumption of foods high in energy in recent years, diseases related to insulin sensitivity, such as type 2 diabetes mellitus (T2DM), obesity, and non-alcoholic fatty liver disease (NAFLD), are extremely common conditions worldwide." (PMID 41303557, 2025). "Type 2 diabetes mellitus (T2DM) is a chronic metabolic disorder characterized by hyperglycemia resulting from insulin resistance and insufficient insulin secretion." (PMID 40424347, 2025). "Type 2 diabetes mellitus (T2DM) involves complex molecular disturbance centered around insulin resistance and pancreatic β-cell dysfunction." (PMID 40076293, 2025). "Another study focusing on type 2 diabetes (T2D) discovered a connection between the insulin signaling cascade and AD." (PMID 41226780, 2025).
type 2 diabetes (continued). "A 2023 review and meta-analysis found that insulin (and insulin secretagogue) use was associated with an increased pancreatic cancer risk, while the use of biguanide and thiazolidinedione (type 2 diabetes medication) carried no risk, or potentially a lower risk of some cancers." (PMID 41573197, 2025). "Youth-onset type 2 diabetes mellitus (T2DM) is an escalating global public health concern, mostly driven by increasing obesity and insulin resistance." (PMID 40630340, 2025). "Type 2 diabetes mellitus (T2DM), which accounts for nearly 95% of cases, primarily results from insulin resistance (IR) and impaired insulin secretion from pancreatic β-cell dysfunction." (PMID 41393929, 2025). "Interestingly, epidemiological and mechanistic links between PD and type 2 diabetes mellitus (T2DM) have suggested that insulin signalling and metabolic dysfunction may contribute to PD pathogenesis." (PMID 41465588, 2025). "There is an unmet need for type 2 diabetes (T2D) treatments in addition to metformin and insulin for adolescents." (PMID 40585887, 2025). "Type 2 diabetes mellitus (T2DM) is characterized by chronic hyperglycemia resulting from impaired insulin production, insulin resistance in peripheral tissues, or a combination of both." (PMID 40909034, 2025). "On pancreatic islets, GLP-1 RAs stimulate glucose-dependent insulin release and inhibit glucagon secretion, improving postprandial glucose control without provoking hypoglycemia—an important feature for insulin-resistant youth and those with prediabetes or type 2 diabetes." (PMID 41300545, 2025). "For a considerable time, the traditional treatment hierarchy for type 2 diabetes (T2D) has included intensified conservative insulin therapy (ICT) for patients in whom relevant therapeutic modifications are no longer possible." (PMID 40264573, 2025). "For example, low IGF-I has been associated with low HDL cholesterol, and reduced insulin sensitivity, both of which are known risk factors for cardiovascular disease (CVD) and type 2 diabetes mellitus (T2DM)." (PMID 40630171, 2025). "Type 2 diabetes mellitus (T2DM) is a chronic metabolic disorder characterized by insulin resistance, impaired insulin secretion, and progressive β-cell dysfunction." (PMID 41146812, 2025). "Likewise, RCTs and retrospective studies have also demonstrated that using these sensor-based glucose monitoring systems is associated with improvements in HbA1c for people with inadequately managed type 2 diabetes treated with basal insulin only or on non-insulin therapies." (PMID 39460755, 2025). "Cells may be harmed by autoimmunity or for unknown causes, resulting in a lack of insulin production in young people with maturity-onset diabetes, while neonatal diabetes may result in a lack of glucose sensing." (PMID 39453501, 2025). "None of the variant groups was significantly associated with the glycaemic phenotypes or type 2 diabetes prevalence after correction for multiple testing, except for the common WT-like G24E variant displaying an elevated estimated insulin response (p=0.0032) (after BMI adjustment, p=0.024)." (PMID 40064676, 2025). "SELENOP administration reduced insulin-stimulated phosphorylation of both the insulin receptor and the protein kinase B (Akt) that can impair insulin signaling in hepatocytes, while genetic knockdown of hepatic Selenop1 alleviated both glucose intolerance and IR in mice with type 2 diabetes." (PMID 40806069, 2025). "Type 2 diabetes mellitus (T2DM) is a chronic metabolic condition characterized by impaired insulin sensitivity and persistent hyperglycemia." (PMID 40426922, 2025). "Interestingly, people with obesity and/or type 2 diabetes have been described to have inverted circadian systems, such that they are more insulin resistant and have lower insulin secretion in the morning than the evening (which is opposite of healthy controls)." (PMID 40018087, 2025).
type 2 diabetes (continued). "Type 2 diabetes mellitus (T2DM) is characterized by metabolic disturbances, primarily centered on impaired insulin secretion and heightened blood glucose levels, which can escalate the risk of severe complications." (PMID 40566565, 2025). "Type 2 diabetes mellitus (T2DM) is a chronic metabolic disorder characterized by persistent hyperglycemia resulting from inadequate insulin secretion or insulin resistance and is influenced by genetic and environmental factors." (PMID 41008530, 2025). "Type 2 diabetes mellitus (T2D) is a chronic metabolic disorder characterized by persistent hyperglycemia due to insulin resistance and impaired insulin secretion." (PMID 40921490, 2025). "In addition, it has been shown that non-diabetic first-degree relatives of patients with type II diabetes may also be insulin resistant and that insulin predicts the development of significant type II diabetes." (PMID 41002997, 2025). "This role in insulin production might be helpful for people with type 2 diabetes." (PMID 39796232, 2025). "Fiber-rich diets that boost colonic SCFA production have consistently shown benefits: improved insulin sensitivity, reduced weight gain, and lower type 2 diabetes (T2D) incidence in cohort studies and clinical trials." (PMID 40871736, 2025). "If the parasympathetic or sympathetic nervous system is not working properly, it might cause type 2 diabetes by lowering how much insulin the body makes, or it might lead to metabolic syndrome by making the body more resistant to insulin." (PMID 40940782, 2025). "Type 2 diabetes mellitus (T2DM) is a serious chronic metabolic disease that occurs in adolescents and adults when the body is unable to use insulin effectively." (PMID 41219907, 2025). "Type 2 diabetes mellitus (T2DM) is a complex metabolic disorder characterized by hyperglycemia, insulin resistance, and impaired insulin secretion, leading to a cascade of microvascular and macrovascular complications." (PMID 40870858, 2025). "It has been shown that mice with genetic ablation of Cav-3 exhibit impaired insulin signaling, abnormal glucose and lipid metabolism, adiposity, and insulin resistance with ligand-induced insulin receptor instability in skeletal muscle, which has similar features to type 2 diabetes." (PMID 40012041, 2025). "Early short‐term intensive insulin therapy (IIT) may induce glycemic remission in type 2 diabetes." (PMID 40747755, 2025). "This meta-analysis aimed to evaluate the efficacy and safety profiles of insulin efsitora in the treatment of type 2 diabetes (T2D)." (PMID 41476918, 2025). "Thus, PAK1-dependent increase in insulin biogenesis genes may be context-dependent, as observed in type 2 diabetes." (PMID 39404845, 2025). "Reduced insulin sensitivity is a crucial contributor to the development and progression of type 2 diabetes mellitus (T2DM)." (PMID 41220711, 2025). "Diabetes is a multisystem metabolic disorder characterized by hyperglycemia, and it could be classified into early-onset Type 1 diabetes (T1D) with immune-mediated beta cell destruction and late-onset Type 2 diabetes (T2D) with beta cell dysfunction and insulin resistance." (PMID 40135071, 2025). "Insulin resistance, a condition where cells in the body become less responsive to insulin, is a key feature of type 2 diabetes mellitus (T2DM)." (PMID 40901177, 2025). "Literature data suggest that apoL1 is associated with type 2 diabetes mellitus (T2DM), and related to impaired HDL metabolism in insulin resistant states." (PMID 41268158, 2025). "Additionally, they may improve insulin sensitivity, helping reduce fat accumulation, particularly in type 2 diabetes patients, where improving insulin resistance is a critical factor in weight management." (PMID 40665981, 2025). "Type 2 diabetes mellitus (T2DM) is a chronic metabolic disorder characterized by high blood glucose levels due to insulin resistance or inadequate insulin production." (PMID 40565836, 2025).
type 2 diabetes (continued). "Despite the promotion of the use of telehealth services, access barriers to insulin, other diabetic therapeutics, and diabetic supplies in the outpatient setting may still exist, resulting in poor hemoglobin A1c control for patients with type 2 diabetes." (PMID 41008502, 2025). "Type 2 diabetes mellitus (T2DM) is a metabolic disorder characterized by chronic hyperglycemia due to inadequate insulin secretion or insulin resistance." (PMID 39854536, 2025). "Additionally, we assessed whether acute exercise and exercise training could potentiate insulin action on plasma BCAAs, and whether these responses remain intact in obesity and type 2 diabetes." (PMID 40404819, 2025). "While cortisol and aldosterone levels have been linked to insulin secretion and resistance in participants without type 2 diabetes, their role in patients with type 2 diabetes remains unclear." (PMID 40296149, 2025). "Type 2 diabetes mellitus (T2DM) is a complex metabolic condition characterized by IR and inadequate compensatory insulin production." (PMID 40664894, 2025). "However, it remains to be clarified whether exercise training and acute exercise potentiate insulin’s ability to suppress plasma BCAAs and to what extent these responses are intact in obesity and type 2 diabetes." (PMID 40404819, 2025). "Sustained improvements in adiponectin levels may enhance metabolic flexibility, improve insulin sensitivity, and potentially contribute to improved metabolic health, which is critical for preventing metabolic diseases such as type 2 diabetes and cardiovascular disorders." (PMID 41323564, 2025). "Although this could modify insulin metabolism, a variety of treatments is unavoidable as, when a youth is diagnosed with type 2 diabetes, treatment is initiated, and therapeutic methods are determined by the severity of hyperglycemia and the choice of a provider in a clinical setting." (PMID 40470991, 2025). "The most widespread form of the disease is type 2 diabetes mellitus (T2DM), which is characterized by chronic hyperglycemia, insulin resistance, and ineffective insulin secretion and action." (PMID 41212880, 2025). "GDF15 has emerged as a promising therapeutic candidate for type 2 diabetes mellitus (T2DM), largely due to its impact on glucose metabolism, insulin sensitivity, and weight regulation." (PMID 40837873, 2025). "Metformin is commonly regarded as the primary medication for individuals with type 2 diabetes mellitus (T2DM) due to its proven ability to lower the blood sugar level as well as improve insulin sensitivity." (PMID 39776799, 2025). "Type 2 diabetes mellitus (T2D) is a chronic metabolic condition involving reduced insulin sensitivity and disrupted blood glucose regulation." (PMID 41225798, 2025). "A recent study involving over 1.6 million patients with type 2 diabetes (T2DM) compared the incidence of 13 obesity-associated cancers among those treated with GLP-1 RAs, insulin, or metformin." (PMID 39796190, 2025). "Similarly, glucagon-like peptide-1 receptor agonists (GLP-1RAs), initially developed for the treatment of type 2 diabetes, have demonstrated promising cognitive benefits, potentially mediated through improved insulin signaling, neuronal survival, and reduced β-amyloid (Aβ) and tau burden." (PMID 40642529, 2025). "Metformin (1,1‐dimethylbiguanidde hydrochloride), an oral biguanide insulin sensitiser, is a well‐established antihyperglycaemic agent for type 2 diabetes mellitus (T2DM) and is used as one of the first‐line medications for GDM." (PMID 40859436, 2025). "However, our results are in line with previous studies in smaller cohorts, which were also unable to demonstrate an effect of exercise training on the ability of insulin to suppress circulating BCAAs in lean individuals, individuals with obesity or individuals with type 2 diabetes." (PMID 40404819, 2025).
type 2 diabetes (continued). "Type-2 Diabetes Mellitus (T2DM) is the result of genetic predisposition, inflammation, and metabolic stress that lead to progressive pancreatic β-cell dysfunction with insufficient insulin secretion, often combined with insulin resistance and metabolic syndrome, resulting in hyperglycemia." (PMID 40725640, 2025). "Reduced insulin sensitivity and glucose effectiveness have been linked to elevated SFA to PUFA ratios in the skeletal muscle cell membrane, which may raise the risk of type 2 diabetes." (PMID 39940428, 2025). "However, acipimox may be most effective when used in conjunction with exercise, as it significantly lowers post‐exercise insulin and glucose levels in individuals with Type 2 diabetes." (PMID 40289598, 2025). "Furthermore, the majority of existing treatments for type 2 diabetes are dependent on the production of insulin, which might, therefore, require an increase in the dose while the disease advances and insulin production declines." (PMID 40430352, 2025). "As the predominant subtype accounting for 90–95% of cases, type 2 diabetes mellitus (T2DM) originates from the synergistic interplay of insulin resistance in key metabolic tissues (skeletal muscle, liver, and adipose) and progressive β-cell dysfunction." (PMID 40395816, 2025). "Among them, the drug of choice for type 2 diabetes mellitus (T2DM) patients, the oral-biguanide metformin, is shown to have insulin-sensitizing and anti-hyperglycemic properties." (PMID 38990489, 2025). "However, considering that insulin and sulfonylureas are still widely used for glycemic management in patients with type 2 diabetes globally, our results retain clinical relevance, although validation studies are needed in patients treated with newer hypoglycemic agents." (PMID 40674363, 2025). "Adding to the complexity, administration of insulin to the brain by the intranasal route may elicit an increased response when measuring cerebral blood flow in insulin-resistant persons with obesity or type 2 diabetes." (PMID 39185744, 2025). "Fmr1 KO mice appear to have high insulin sensitivity, as well as lower amounts of blood glucose and fat, which is surprising given that some phenotypes are rescued by metformin, the first-line drug to treat Type 2 Diabetes because of its ability to decrease blood glucose." (PMID 41037592, 2025). "The medical illness known as type 2 diabetes mellitus (T2DM) is brought on by an increased blood sugar (glucose) level, which is brought on by the body’s inability to produce enough insulin." (PMID 40003984, 2025). "Despite these limitations, this study is important given that a single or few hypoxic exposures may have clinical implications, such as, the improved insulin sensitivity observed following single intermittent exercise sessions in hypoxia observed among type 2 diabetics." (PMID 40214167, 2025). "Although this may enhance insulin‐mediated responses under physiological conditions—such as during exercise—chronic hyperlactatemia may worsen hyperinsulinemia and β‐cell exhaustion in Type 2 diabetes." (PMID 40289598, 2025). "This includes technical innovations in glucose monitoring and insulin delivery resulting in improved glycemic control for type-1 diabetes, and more so in view of the increased complexity of the therapeutic background in patients receiving treatment for type 2 diabetes." (PMID 40940761, 2025). "Type 2 diabetes mellitus (T2DM) is a chronic metabolic disorder characterized by reduced insulin efficacy and pancreatic β-cell impairment." (PMID 41311805, 2025). "Furthermore, insulin sensitivity is increased even after a single bout of exercise, for a period up to ~48 h, in both healthy lean individuals and individuals with type 2 diabetes." (PMID 40404819, 2025). "Type 2 diabetes mellitus (T2DM) is a chronic and prevalent metabolic disorder characterized by insulin resistance, impaired insulin secretion, and hyperglycemia, affecting millions worldwide." (PMID 41356012, 2025).